SRSF2 (serine and arginine rich splicing factor 2)
Diseases named in the same sentence as SRSF2 in open-access papers (continued):
Sharing a sentence is not in itself a finding about the gene and the disease.
cancer (71 papers, 2010 to 2026). A tumor composed of atypical neoplastic, often pleomorphic cells that invade other tissues. "Mutations in SRSF2 are associated with various cancers, and elevated expression of SRSF2 contributes to the advancement of HCC and its unfavorable prognosis in patients." (PMID 39336772, 2024). "Increasing evidence has confirmed that SRSF2 regulated splicing variants related to cancer and immune disorders." (PMID 38528189, 2024). "Our findings showed that FTO was somewhat linked, either positively or negatively associated with SRSF2 in 19 cancer types." (PMID 38015716, 2023). "Recently, it has been found that expression changes of both tumor-type-specific and pan-cancer splicing factors (comprising hubs of SRSF2/3/7) modules are frequently associated with MYC activity in several cancer types." (PMID 37443779, 2023). "As a well-characterized splicing regulator, SRSF2 regulated AS events in a highly position-dependent manner and has been implicated essential roles in vertebrate development and cancer progression." (PMID 36623729, 2023). "Because tumor cells depend on wild-type SFs for survival, these drugs are particularly effective in killing cancer cells with already impaired splicing machinery due to mutations in SFs, such as SRSF2 and SF3B152." (PMID 33753867, 2021). "Through the regulation of cancer-associated splice variants, SRSF2 have been implicated in many types of cancer, including lung carcinoma, hepatocellular carcinoma, and RCC." (PMID 31838573, 2020). "We also detected synthetic interactions between sftb-1 mutants and cancer-related mutations in uaf-2/U2AF1 or rsp-4/SRSF2, demonstrating that this model can identify interactions between mutations that are mutually exclusive in human tumors." (PMID 31634348, 2019). "Knockdown of SRSF2 in HCC cells resulted in alternatively spliced variants in cancer-related genes including exon inclusion of GCH1, STK39 and TERF1 (TRBF1)." (PMID 31162605, 2019). "Importantly, many cancer-specific splice variants are dysregulated by the changes in SRSF2 expression." (PMID 36623729, 2023). "The mutation of rs3200401 may lead to the downregulation of SRSF2 phosphorylation and a change in tumor-related gene shearing, thus affecting the occurrence and development of cancer." (PMID 35208500, 2022). "Functional mutations of SRSF2 drive the cancer genesis of hematopoietic cells." (PMID 32883226, 2020). "Splicing factor SRSF2 is frequently mutated or up-regulated in human cancers." (PMID 32372053, 2020). "For this purpose, we took advantage of the cancer-associated over-expression of SRSF2, as it may occur in NSCLC." (PMID 24428911, 2014). "In cancer, recurrent mutations in splicing factors such as SF3B1, SRSF2, and U2AF1 are frequently observed, and these aberrations likely induce translational dysregulation associated with ORF dominance." (PMID 41596295, 2026). "Two of the top candidates, BCL-2 and SRSF2, are known to be non-synonymous drivers of cancer as cataloged in the Cancer Gene Census." (PMID 38062391, 2023). "Supportively, previous studies showed the essential roles of SRSF2 in cancer cell growth and survival." (PMID 36623729, 2023). "SRSF2 regulated cancer-related SLMAP and CETN3 to generate different splice variants with distinct functions in cancer." (PMID 36623729, 2023). "Cancer-related splice variants in SLMAP and CETN3 were validated by regulation of SRSF2 at the molecular level." (PMID 36623729, 2023). "As synonymous mutations can perturb mRNA translation initiation and elongation processes, it is possible that SRSF2 synonymous mutations alter RRM binding affinity and contribute to a global transcriptional profile change in cancer cells." (PMID 38062391, 2023). "Based on our candidate selection process, three SFs are expected to be FL TERT promoters (HNRNPM in iPSCs; SRSF2 in both iPSCs and cancer cells; U2AF2 in cancer cells)." (PMID 37531400, 2023).
cancer (continued). "Other splicing inhibitors such as sudemycin D6 or E7107 also display stronger cytotoxic effects on splicing factor–mutant cancer cells, including mutations in SF3B1 and other splicing factors such as U2AF1 and SRSF2." (PMID 37562845, 2023). "There is strong evidence that mutations of splicing components SRSF2 and SF3B1 cause cancer in part by enhancing the inclusion of pseudoexons with in-frame stop codons for two genes EZH2 and BRD9, respectively." (PMID 35188075, 2022). "Because of the significant role SRSF2 plays in alternative RNA splicing in apoptotic pathways, the dysregulation of miRNAs that target SRSF2 is a fingerprint in many types of cancers." (PMID 34769047, 2021). "Another miRNA, miR-193a-3p, which is upregulated in multiple other cancers, has been shown to directly target SRSF2 in nasopharyngeal cancer." (PMID 34769047, 2021). "H3B has also shown a preferential antitumor activity in cell cultures and patient-derived xenograft models presenting cancer-associated mutations of SF3B1 and SRSF2." (PMID 34681880, 2021). "Recent studies on cancer genomes have revealed that recurrent somatic mutations of genes encoding RNA splicing factors (e.g. SF3B1, U2AF1, SRSF2, ZRSR2) lead to altered splice site preferences, resulting in cancer-specific mis-splicing of genes." (PMID 33427197, 2021). "SRSF2 promotes apoptosis through alternative RNA splicing of specific cancer genes, such as c-flip, caspases-8 and -9, and Bcl-x, to their pro-apoptotic isoforms, and a decrease in its expression is associated with the inhibition of apoptosis." (PMID 34769047, 2021). "Caffeine has been shown to increase the expression of SRSF2 in cancer cells and to alter the splicing of cancer-related proteins." (PMID 34831035, 2021). "Collectively, the most frequently mutated cancer myeloid genes were ASXL1 (47%), TET2 (37%), RUNX1 (27%) and SRSF2 (17%)." (PMID 30787430, 2019). "Caffeine-induced serine/arginine-rich splicing factor 2, SRSF2, and SRSF3 are required for the alternative splicing of a subset of cancer-associated genes." (PMID 29254178, 2017). "In summary, we show for the first time that decreased expression of SRSF2 in ccRCC contributes to protection of cancer cells viability." (PMID 27690003, 2016). "The enhanced viability of cancer cells with low SRSF2 expression fits well the observed changes in alternative splicing and expression of apoptotic genes." (PMID 27690003, 2016). "Still, reduced expression of SRSF1 and SRSF2 proteins in the cancer cells weakly correlated with signature of mirtronic miRNA expression." (PMID 27019673, 2016). "An overall downregulation of cancer hallmark genes was found when splicing factors such as SRSF2 and SF3B1 were mutated in UM, unlike other kinds of cancers." (PMID 38920653, 2024). "SRSF2 expression correlates with cancer progression in malignant ovarian tissues." (PMID 39105794, 2024). "Interestingly, SRSF2 belongs to the family of SFs itself and contributes to the carcinogenesis of multiple cancers via alternative splicing." (PMID 35614517, 2022). "The dysregulation of splicing regulators has been shown to cause numerous abnormal alternative splicing events in cancers and SRSF2 is no exception." (PMID 31162605, 2019). "The upregulation of SRSF2 protein has been confirmed in many cancers." (PMID 32039035, 2019). "No cancer-related genes showed SRSF2-associated splicing alterations characterized by a PSI value greater that 10%, and a more than 2-fold increase compared to controls." (PMID 30194306, 2018). "Accordingly, tumor-promoting roles of SRSF1 and SRSF2 have been reported in various cancer types." (PMID 27019673, 2016).
cancer (continued). "Finally, we found that overexpression of well-known splicing factors SRSF1 and SRSF2 increased the abundance of some mirtron-derived miRNAs in colorectal HCT116 cancer cells." (PMID 27019673, 2016). "Interestingly, it was shown that SRSF2 contributes to chemoresistance in cancers of liver, bladder, and lung." (PMID 27690003, 2016). "Besides SRSF2, miR-193a-3p’s influence on the cancer chemoresistance is expected to be accomplished via repression of its other targets." (PMID 25311867, 2014). "However, despite adverse treatment outcomes, no targeted drugs exist for cancers with SRSF2 mutations." (PMID 41279606, 2025). "Host RNA splicing factor SR proteins, including SRSF1(ASF/SF2), SRSF2 (SC35), SRSF3 (SRp20), and SRSF10 (SRp38/SRrp40), are also upregulated in HPV-positive cervical precancer lesions and cancer tissues." (PMID 35563334, 2022). "Since 2011, recurrent somatic mutations have been identified in a number of spliceosome components in human malignancies through the Cancer Genome Project, such as U2AF1 (U2AF35), SRSF2 (SC35), SF3B1 (SF3B155 or SAP155), and ZRSR2 (URP)." (PMID 32905346, 2020). "Exome sequencing studies have revealed a restricted pattern of somatic mutations in U2AF1/U2AF2 and other genes involved in 3′ss recognition in cancer cells, including SF3B1, ZRSR2, SF1, SF3A1, PRPF40B, and SRSF2 (reviewed in7)." (PMID 26732650, 2016). "For example, SRSF1 and SRSF2 presented relatively higher CNV amplification in the vast majority of cancer types, with the lack of deep deletion." (PMID 38015716, 2023). "Previous studies have demonstrated that most SRSFs were extensively dysregulated with oncogenic roles through regulating the AS of various cancer-related genes in many cancers such as lung (SRSF1, SRSF5), breast (SRSF3), colon (SRSF1, SRSF10), liver cancers (SRSF2), and glioma (SRSF1, SRSF3)." (PMID 37558679, 2023). "This does not necessarily contradict our mechanistic evidence that MBD2_v2 expression in TNBC cells depends on SRSF2; it may reflect that differences in SRSF2 mRNA levels are small and challenging to discern in analysis of RNA from patient FFPE cancer specimens." (PMID 30636104, 2019). "These outcomes of TERT AS also matched our predictions that SRSF2 and U2AF2 were FL TERT promoters in cancer cells, while HNRNPM would not impact splicing of TERT exons 7/8." (PMID 37531400, 2023).
tumor (62 papers, 2010 to 2026). "This study identified SRSF2, a splicing factor whose protein levels are associated with the distribution of membranous to secreted PD-L1 splice variants, and further investigated SRSF2 gene expression and its tumor biological relevance." (PMID 41228255, 2025). "IDH2 mutations change the splicing effects of mutated SRSF2 and lead to more profound ASEs than single mutations alone, as well as lethal myelodysplasia with proliferative characteristics in vivo and enhanced tumor self-renewal." (PMID 38302461, 2024). "A study on SRSF2-mutated neoplasms revealed that co-mutation of SRSF2 and other splicing factors had a clear predominance of blastic phenotype." (PMID 38714876, 2024). "Upregulation of serine/arginine-rich splicing factor 2 (SRSF2) is significantly associated with a higher tumor grade and a poor prognosis in patients with HCC." (PMID 39202384, 2024). "CTX-712 is a novel Clk Inhibitor that has been found to exert an anti-tumor effect in an SRSF2-mutated xenograft model." (PMID 34868917, 2021). "Mutations in splicing factor 3B subunit 1 (SF3B1) and serine and arginine rich splicing factor 2 (SRSF2) occur in intermediate risk tumours 22,27." (PMID 34149931, 2021). "Herein, we determined that serine/arginine-rich splicing factor 2 (SRSF2) is a target for blocking the tumor microenvironment-associated immunosuppressive effects." (PMID 31838573, 2020). "The decrease in the ability of patients to accumulate T cells, such as Th1 cells, which play crucial roles in modulating the killing of tumour cells may cause worse outcomes for SRSF2 mutant patients." (PMID 39235452, 2024). "Furthermore, the SRSF2-affected splicing targets were associated with tumor-related functions, such as cell cycle, cell migration, MAPK cascade, and ER to Golgi vesicle-mediated transport." (PMID 36623729, 2023). "SRSF2 specifically encodes serine/arginine-rich proteins that bind exonic splicing enhancers, resulting in misregulated exon inclusions that causes an aberrant splicing pattern of many genes including the tumor suppressor genes ARMC10 and EZH2." (PMID 34771666, 2021). "All these data suggest that SRSF2 may be a therapeutic target to block tumor-associated suppressive pathways." (PMID 31838573, 2020). "For experiments designed to more directly assess whether increased expression of MBD2_v2 and SRSF2 plays a causative role in increased tumor formation, we stably modified the levels of MBD2_v2 or SRSF2 in TNBC cells prior to inoculation." (PMID 30636104, 2019). "SRSF2 enhances anti-tumor immune responses by affecting H3K27Ac levels of related genes and the recruitment of STAT3, providing a new idea for reversing the depletion of TILs." (PMID 40129567, 2025). "The impact of SRSF2 expression was further analyzed by RNA-Seq-based transcriptome analyses of respective SRSF2-overexpressing and knockdown transfectants with regard to which other tumor immunology- or tumor biology-relevant genes were influenced by SRSF2." (PMID 41228255, 2025). "SRSF2 is overexpressed in depleted T cells and is involved in the depletion of tumor-infiltrating lymphocytes (TILs)." (PMID 40129567, 2025). "To further analyze the deeper impact of the splice factor SRSF2 on tumor biology, we searched for additional transcripts that are dysregulated either by SRSF2 overexpression or by SRSF2 downregulation." (PMID 41228255, 2025). "For a more in-depth characterization of the splice factor SRSF2, its expression was examined using immunofluorescence in human tumor-free renal tissue." (PMID 41228255, 2025). "In contrast, larger vessels from EGFR-expressing tumours were enriched for Birc2 (survivin), Socs2 (suppressor of cytokine signalling 2) and Srsf2 (serine and arginine-rich splicing factor 2)." (PMID 38570528, 2024). "UM tumors often harbor a tumor-initiating mutation in GNAQ or GNA11 with secondary mutation in EIF1AX, SF3B1, SRSF2, or BAP1 that determines metastatic potential." (PMID 34771666, 2021).
tumor (continued). "Here, we identified a tumor suppressor role of the acetyltransferase p300 in clinically relevant MDS models driven by mutations in the epigenetic regulators TET2, ASXL1, and SRSF2." (PMID 34622806, 2021). "Other examples from this study include well-described tumor-promoting genes such as SRSF2, DNMT3A, ATM, BRCA1 and PKM, for which Tax- and HBZ-alternative splicing events are now associated with ATLL for the first time." (PMID 34543356, 2021). "Even though these results were obtained with a limited number of samples, it deserves future analysis to corroborate the correlation between the expression of ARHGEF10 and SRSF2 in a large number of tumor tissues." (PMID 32635183, 2020). "In the current study, we found that the inhibition of SRSF2 expression in TILs significantly improves its anti-tumor immune response via the epigenetic regulation of multiple immune checkpoint molecules." (PMID 31838573, 2020). "Taken together, these results demonstrated that TILs isolated from tumor tissues expressed higher levels of multiple immune checkpoints and that SRSF2 regulates the expression of these immune checkpoints." (PMID 31838573, 2020). "The in vitro and in vivo experimental data presented here support that the SRSF2–MBD2_v2 regulatory axis is a feature necessary for maintenance of TNBC tumor‐initiating CSCs that can be induced to expand the CSC fraction." (PMID 30636104, 2019). "The results of these experiments suggest that SRSF2 is not only crucial to normal liver development, but also to tumor growth." (PMID 31162605, 2019). "Sanger sequencing covering the U2AF1 (exon 2 and 7) hotspots and SRSF2 (exon 1 and 2) was performed on DNA extracted from tumor tissue." (PMID 31426461, 2019). "MBD2_v2 overexpression significantly increased tumor initiation capacity of TNBC cells in lean mice, and SRSF2 knockdown, which decreased MBD2_v2 expression, significantly hindered tumor formation capacity in the more tumorigenic context of DIO mice." (PMID 30636104, 2019). "SRSF2 (also referred to as SC35) was demonstrated to interfere with the tumor-suppressive signature of the KLF6 gene by inducing the generation of exon 1a-included transcripts, consequently encoding the DNA-binding domain-deficient isoform." (PMID 29283381, 2017). "Western blot performed in eight matched pairs of tumour and control samples revealed moderate-to-strong reduction of SRSF2 protein level." (PMID 27690003, 2016). "In our previous study, we showed that miR-193a-3p promotes Pa chemoresistance in BCa cells in tumor xenografts of nude mice by repressing three of its targets in the tumor tissues: SRSF2, PLAU and HIC2." (PMID 25991669, 2015). "In order to validate these IHC results, SRSF2 protein expression was studied by western blotting in 6 of the 107 tumor samples and their matched normal lung tissues." (PMID 23071587, 2012). "Next, we investigated the status of SRSF2 and its phosphorylated form (P-SRSF2) in the same series of tumor samples by IHC." (PMID 23071587, 2012). "Furthermore, SRSF2 overexpression and its direct involvement in tumor progression have been observed in lung tumors." (PMID 41228255, 2025). "While ASXL1 and SRSF2 mutations may reflect age-related clonal hematopoiesis, SETBP1 is more strongly associated with secondary AML, CMML, and aCML—often co-occurring with ASXL1 and SRSF2 in those neoplasms." (PMID 41278291, 2025). "Finally, RNAscope in situ hybridisation (ISH) analysis further confirmed the presence of distinct transcripts (Socs2, Srsf2, Birc2) in endothelial cells associated with MES-GSC-driven and EGFR expressing tumours." (PMID 38570528, 2024). "Collectively, our data indicated that SRSF2 functions as a modulator of the anti-tumor response of T cells and may be a therapeutic target for reversing the exhaustion of TILs." (PMID 31838573, 2020). "SRSF2 has been reported to be involved in a multiple biological processes and tumor progression." (PMID 32372053, 2020).